TAS2R38 (taste 2 receptor member 38)
Description:
Receptor that may play a role in the perception of bitterness and is gustducin-linked. May play a role in sensing the chemical composition of the gastrointestinal content. The activity of this receptor may stimulate alpha gustducin, mediate PLC-beta-2 activation and lead to the gating of TRPM5 (By similarity).
Synonyms: T2R38; T2R61; PTC; THIOT
Tractability: Antibody: its Gene Ontology location is reachable by antibodies, with high confidence; UniProt predicts a signal peptide or a membrane-spanning region. PROTAC: a small molecule that binds it is known.
Target class: Membrane receptor; Taste receptor (taste family GPCR); Taste family G protein-coupled receptor
Gene: Protein-coding gene on chromosome 7 (141,972,631 to 141,973,773, reverse strand). Ensembl gene ENSG00000257138.
Subcellular location: Membrane
Pathways (Reactome):
Signal Transduction: Class C/3 (Metabotropic glutamate/pheromone receptors); G alpha (i) signalling events
Sensory Perception: Sensory perception of sweet, bitter, and umami (glutamate) taste
Gene Ontology:
Molecular function: bitter taste receptor activity; G protein-coupled receptor activity
Biological process: detection of chemical stimulus involved in sensory perception of bitter taste; G protein-coupled receptor signaling pathway; sensory perception of taste
Cellular component: plasma membrane; membrane
Genetic constraint (gnomAD): Loss-of-function variants: 11 observed, 15.5 expected, observed/expected ratio (o/e) 0.71, 90% interval 0.45 to 1.17. The upper end of that interval is the gene's LOEUF score, 1.17, which puts it in group 5 of 6, group 1 being the genes least tolerant of losing a copy. Missense variants: 316 observed, 369.27 expected, observed/expected ratio (o/e) 0.86, 90% interval 0.78 to 0.94. Synonymous variants: 129 observed, 144.68 expected, observed/expected ratio (o/e) 0.89, 90% interval 0.77 to 1.03.
Homologues: Orthologues: chimpanzee TAS2R38 (98% identical), macaque TAS2R38 (95% identical), dog TAS2R38 (70% identical), mouse Tas2r138 (65% identical), tropical clawed frog t2r15 (23% identical), tropical clawed frog t2r2 (23% identical), tropical clawed frog t2r10 (22% identical), tropical clawed frog tas2r7 (22% identical), tropical clawed frog tas2r13 (21% identical), tropical clawed frog t2r8 (20% identical), tropical clawed frog tas2r4 (20% identical), tropical clawed frog t2r3 (19% identical), and 6 more. Paralogues in human: TAS2R3 (31% identical), TAS2R7 (27% identical), TAS2R43 (27% identical), TAS2R50 (27% identical), TAS2R10 (26% identical), TAS2R42 (26% identical), TAS2R46 (26% identical), TAS2R31 (26% identical), TAS2R30 (26% identical), TAS2R13 (25% identical), TAS2R14 (25% identical), TAS2R9 (25% identical), and 11 more.
Diseases named in the same sentence as TAS2R38 in open-access papers:
TAS2R38 is named in the same sentence as 70 diseases in open-access papers, as found by Europe PMC text mining. Sharing a sentence is not in itself a finding about the gene and the disease. The quoted sentences say what the papers report.
Obesity (20 papers, 2013 to 2025). Accumulation of substantial excess body fat. "Our key findings indicate that variations in the bitter taste receptor gene TAS2R38 were nearly associated with obesity parameters, such as BMI% and BMIz, and significantly with the frequency of SSB consumption." (PMID 41007057, 2025). "This study explored the associations between genetic variants in taste receptor genes, specifically TAS1R2 and TAS2R38, with obesity risk and SSB consumption among Kuwaiti adolescents." (PMID 41007057, 2025). "Our focus on TAS1R2 and TAS2R38 provides insight into culturally relevant dietary behaviors and the heightened obesity risk among adolescents in Kuwait, a region that remains underrepresented in nutrigenomics research." (PMID 41007057, 2025). "The TAS2R38 genotype has been linked to the risk of several chronic conditions, such as obesity, cardiometabolic diseases, and colorectal cancer, potentially through its influence on dietary intake." (PMID 40498099, 2025). "TAS2R38 gene polymorphisms are associated with different diseases from obesity, through gastric and colorectal cancer, PCD, CF, and CRS, to Parkinson’s disease." (PMID 38255273, 2024). "Lastly, previous studies have found differences in the obesity risk related to TAS2R38-rs713598, FTO-rs9939606, and CLOCK-rs4580704, which is consistent with our findings." (PMID 36771415, 2023). "This is supported by a review, and a recent study that found a lower preference for bitter-tasting food and the presence of the (C/G) variant of the TAS2R38 gene (bitter-tasting receptor) were associated with the development of obesity." (PMID 37107436, 2023). "The association between TAS2R38 and obesity risk such as body fat percentage (normal versus overfat) was analyzed." (PMID 35223410, 2021). "In this study, gender but not age showed an association with obesity risk (data not shown); therefore, gender was adjusted in the odds ratio calculation for the risk of TAS2R38 diplotypes to obesity." (PMID 35223410, 2021). "A large observational study in Spain revealed a significant association between obesity and the TAS2R38 AVI/AVI haplotype in females (N = 1319)." (PMID 32708215, 2020). "Such obesity risk modified by the TAS2R38 genetic variation was also maintained in the adjusted models: The OR for the CT genotype was 1.33 (95% CI: 1.06–1.67) and for the TT genotype was 1.75 (95% CI: 1.31–2.36)." (PMID 31438650, 2019). "A number of studies including subjects of multiple ethnicities, ages and geographical regions have been conducted to investigate the associations between TAS2R38 polymorphisms and body size and obesity, yet the findings are still controversial." (PMID 31438650, 2019). "Females with the TAS2R38 rs10246939 variation showed an increased risk of obesity based on the number of T alleles." (PMID 31438650, 2019). "Second, the TAS2R38 rs10246939 variation was significantly associated with dietary intake, body size and risk of obesity mainly in females." (PMID 31438650, 2019). "In conclusion, TAS2R38 rs10246939 variation was associated with Koreans’ dietary intake and increased their risk of obesity." (PMID 31438650, 2019). "Further studies are necessary to examine the applicability of TAS2R38 genetic variations as a predictive marker of the risk of obesity and metabolic diseases." (PMID 31438650, 2019). "Bitterness phenotype or TAS2R38 genetic variations have been associated with weight, body mass index (BMI), and obesity." (PMID 31438650, 2019). "While TAS2R38 has been well studied, more information is needed on the relationship between other T2R gene polymorphisms and risk for obesity." (PMID 30241292, 2018). "A large observational study reported a significant association between risk for obesity and the TAS2R38 AVI/AVI haplotype in females." (PMID 30241292, 2018).
Obesity (continued). "Given that genotypes are determined at birth and generally remain independent of external lifestyle factors, the observed result in our study supports the hypothesis that TAS2R38 variants might exert a meaningful influence on adolescent obesity development." (PMID 41007057, 2025). "Genetic variations in taste receptor genes, particularly TAS1R2 and TAS2R38, may influence taste preferences, dietary intake, and obesity risk." (PMID 41007057, 2025). "TAS2R38 is the most-studied subtype, and its genetic variants have been associated with several behavioral habits, e.g., smoking and diet, with an increased risk of the development of colorectal and gastric cancers, dysbiosis, and obesity." (PMID 40076714, 2025). "However, it is important to note that the relationship between these TAS2R38 variants and BMI, particularly in the context of obesity, anorexia, or normal body weight, necessitates more in-depth research to unravel the underlying mechanisms." (PMID 38248819, 2023). "This study examined whether the genetic variant rs10246939 C > T in TAS2R38 was associated with food intake and body size as well as obesity risk." (PMID 31438650, 2019). "TAS2R38 rs10246939 T allele may be associated with an increased dietary intake of fruit and a higher risk of obesity in Korean females." (PMID 31438650, 2019). "TAS2R38 polymorphisms could be associated with obesity development." (PMID 35223410, 2021). "Moreover, the use of bioelectrical impedance analysis for evaluation of fat mass and the effect of population stratification in admixed populations should be considered in future studies to confirm the contribution of TAS2R38 SNPs to the risk of developing obesity." (PMID 35223410, 2021). "However, TAS2R38 rs10246939 was a significant obesity risk-modifying factor in the female subjects." (PMID 31438650, 2019). "We therefore investigated associations between TAS1R2 and TAS2R38 variants, SSB intake, and obesity risk in Kuwaiti adolescents, aiming to contribute to the growing field of nutrigenetics and to inform future personalized nutrition interventions." (PMID 41007057, 2025). "This study examined associations between TAS1R2 and TAS2R38 polymorphisms, sugar-sweetened beverage (SSB) intake, and obesity risk in Kuwaiti adolescents." (PMID 41007057, 2025). "The same gene–pattern interactions were found for TAS2R38-rs713598 and the midpoint of sleep in the same obesity parameters, the BMI (p = 0.032) and waist circumference (p = 0.010)." (PMID 36771415, 2023). "In the additional multivariate-adjusted model adjusted for sex, age, obesity, smoking, and medication, we found the same statistically significant differences, except for in TAS2R38-rs713598 and wake timing, where we obtained a trend (p = 0.091)." (PMID 36771415, 2023). "We selected three genes as detailed in the methods (the TAS2R38 gene, related to bitter taste perception; FTO, the obesity-associated gene; and the CLOCK gene, one of the core clock genes involved in the regulation of the circadian timing system)." (PMID 36771415, 2023). "Moreover, significant gene–sleep interactions were detected between the midpoint of sleep and the TAS2R38-rs713598 (p = 0.032), FTO-rs9939609 (p = 0.037), and CLOCK-rs4580704 (p = 0.004) polymorphisms which played a role in determining obesity phenotypes." (PMID 36771415, 2023). "The expression of TAS2R38 in the intestines might influence energy balance and intraluminal changes occurring in obesity." (PMID 35223410, 2021). "Additionally, the mRNA expression of TAS2R4, TAS2R10 and TAS2R38 was significantly altered by obesity in a tissue-dependent manner." (PMID 32708215, 2020). "The similar trend toward was found regarding TAS2R38 rs10246939 T allele and the increased risk of obesity in males, but the statistical power was lacked (adjusted OR for TT genotype: 1.45, 95%CI: 0.95-2.22, p < 0.081)." (PMID 31438650, 2019).
Obesity (continued). "Although more detailed statistical analyses in the larger cohort are required, current study suggested that, as a genetic predictive marker, TAS2R38 bitterness receptor variations may have a large implication in obesity prevention and treatment." (PMID 31438650, 2019). "Interestingly, a third group of genes (CPE, NPY5R, DRD3, TAS2R38, SLC18A1, G6PC3, NPY1R, and VLDLR) was highly associated with both neurological and obesity concepts." (PMID 23544116, 2013). "The potential mechanisms linking TAS2R38 polymorphisms to obesity risk may involve both gustatory and non-gustatory pathways." (PMID 41007057, 2025). "Furthermore, our findings that Tas2r138 mRNA is upregulated in high-fat diet-induced obesity in mice and that TAS2R38 mRNA and protein are upregulated in the colon of obese/overweight subjects suggest that intraluminal changes in obesity affect these receptors’ expression." (PMID 37836428, 2023). "Furthermore, the subjects who were unable to taste bitterness due to genetic variations of the bitter taste receptor TAS2R38 were supposed to consume more dietary fat and, therefore, might develop obesity." (PMID 35887721, 2022). "The lack of evidence for an association provides us with confidence that, at the population level, the PROP/PTC taste perception and TAS2R38 genotype are unlikely to be a predictor for obesity in Europeans." (PMID 40498099, 2025). "In Kuwait, where obesity prevalence is among the highest globally, no prior studies have investigated TAS1R2 and TAS2R38 variants in relation to SSB consumption in adolescents." (PMID 41007057, 2025). "There have been ties between the non-taster recessive haplotypes of TAS2R38, the taste receptor gene that mediates the ability to taste PROP, and greater risk of obesity." (PMID 30970617, 2019). "It has been suggested that the TAS2R38 haplotype may be a predictor of obesity; however, larger cohort studies have not confirmed an association between TAS2R38 and obesity despite the association of this polymorphism with nutrition." (PMID 39458556, 2024).
chronic rhinosinusitis (13 papers, 2016 to 2024). Chronic form of sinusitis. "The incipient role of TAS2R38 and its polymorphisms in chronic rhinosinusitis inspired a study involving patients with cystic fibrosis homozygous for the pathogenic ΔF508 mutation." (PMID 32708215, 2020). "For example, TAS2R38 polymorphisms are strongly related to upper respiratory infections and the risk of chronic rhinosinusitis." (PMID 32033224, 2020). "Polymorphisms of TAS2R38 have been proven to have an influence on the course of chronic rhinosinusitis and upper airway defensive mechanisms." (PMID 32708215, 2020). "Patients with chronic rhinosinusitis who have gene allelic frequencies favoring dysfunctional TAS2R38 are at higher risk for sinus surgery than those who are homozygous for functional TAS2R38 alleles." (PMID 30542293, 2018). "Most of the studies concerning chronic rhinosinusitis confirm the differences in TAS2R38 polymorphism distribution between CRS patients and healthy controls, highlighting that the nonfunctional genotype (AVI/AVI) is more frequent among CRS patients than in the general population." (PMID 38255273, 2024). "In addition, a large number of studies have associated the TAS2R38 genotype with upper respiratory tract infection susceptibility, and identified TAS2R38 single nucleotide polymorphisms associated with the course of chronic rhinosinusitis." (PMID 36529808, 2022). "It was established that single nucleotide polymorphisms (SNPs) in the TAS2R38 gene may contribute to individual differences in susceptibility to respiratory infections, in particular, to chronic rhinosinusitis (CRS)." (PMID 32708215, 2020). "In comparison, previous studies have demonstrated that variations in the TAS2R38 gene, specifically single nucleotide polymorphisms (SNPs), have the potential to influence an individual’s susceptibility to respiratory infections, particularly chronic rhinosinusitis (CRS)." (PMID 38397921, 2024). "Finally, it was established that single nucleotide polymorphisms (SNPs) in the TAS2R38 gene may contribute to individual differences in susceptibility to respiratory infections—in particular, to chronic rhinosinusitis (CRS)." (PMID 35806350, 2022). "We investigated the expression and distribution of two T2Rs, T2R14 and T2R38, in patients with chronic rhinosinusitis (CRS) and correlated the results with fractional exhaled NO (FeNO) levels and genotype of the T2R38 gene (TAS2R38)." (PMID 36901926, 2023).
upper respiratory infection (12 papers, 2013 to 2025). "Homozygous patients for the PAV variant are less susceptible to respiratory infections than homozygous patients for the AVI variant who have altered TAS2R38-dependent responses, and heterozygous patients." (PMID 40280971, 2025). "For example, polymorphisms of the TAS2R38 gene are linked to significant differences in the ability of upper respiratory cells to clear and kill bacteria, and consequently may be involved in susceptibility to upper respiratory infection and recalcitrant sinusitis." (PMID 35896963, 2022).
cystic fibrosis (8 papers, 2019 to 2025). Autosomal recessive disorder caused by pathogenic variants in the CFTR gene (cystic fibrosis transmembrane conductance regulator), which encodes a chloride and bicarbonate channel expressed in epithelial cells, and follow the diagnosis criteria. "In cystic fibrosis patients, TAS2R38 polymorphisms may also play a role in pulmonary P. aeruginosa lung colonization." (PMID 39979526, 2025). "In addition, polymorphisms in the TAS2R38 gene have also been linked with patients with cystic fibrosis." (PMID 34831117, 2021). "The TAS2R38 genotype may act as a disease modifier for cystic fibrosis." (PMID 39317733, 2024).
dental caries (8 papers, 2018 to 2026). The decay of a tooth, in which it becomes softened, discolored, and/or porous. "Previous studies evaluating the role of taste receptors in dental caries risk/protection have identified TAS2R38 as a key player." (PMID 36404915, 2022). "Hence, clinical research has demonstrated that gene variants of TAS2R38 are associated with a defensive impact against dental caries." (PMID 38397921, 2024). "Interestingly, TAS2R38 rs1726866 was associated with Candida albicans, which has been implicated in dental caries development." (PMID 36404915, 2022). "Specifically, TAS2R38 as has been associated with dental caries in previous studies." (PMID 34311721, 2021). "In summary, this study found multiple associations near genes that may play important roles in dental caries, such as TAS2R38, TAS2R3, TAS2R4, TASR25, DLX3 and DLX4, several of which have plausible biological functions relevant to tooth development and cariogenesis." (PMID 34311721, 2021). "A candidate gene study found that the taste receptor genes, TAS2R38 (bitter) and TAS1R2 (sweet), were associated with dental caries in primary and mixed dentition, respectively, in the COHRA1 cohort, one of the five cohorts included in this study." (PMID 36672800, 2022). "The current study aims to examine TAS2R38 genotype frequency distribution among adult dental patients and to explore the relationships between TAS2R38 genotype and the presence of oral diseases (dental caries and periodontal disease) in the Thai population." (PMID 35090440, 2022). "This study also supported the role of taste receptor genes in dental caries (TAS2R38, TAS2R3, TAS2R4, TASR25), which have been associated with dental caries in previous studies." (PMID 34311721, 2021). "Two genes, namely, taste 2 receptor member 38 (TAS2R38) and taste 1 receptor member (TAS1R2), have been identified to be important in taste sensing and to be associated with dental caries risk and/or protection." (PMID 29849633, 2018). "Several previous studies have identified an association between several genes and dental caries, including genes related to enamel formation such as AMBN, AMELX, and ENAM; taste receptor genes such as TAS2R38, TAS1R2; immune-related genes such as HLA; and saliva genes such as MUC5B, PRH1." (PMID 38414691, 2024). "Further, taste receptor genes, specifically TAS2R38, influence bitter perception and dietary habits that are hypothesized to lead to consuming more sweets in the diet and thus leading to dental caries." (PMID 34311721, 2021). "An interesting suggestive association for the permanent dentition DFT was at 7q34 (lead SNP rs11197981; P = 1.11 × 10−6), approximately 200 kb downstream of taste receptor genes (TAS2R38, TAS2R3, TAS2R4, TASR25), which have plausible roles in dental caries." (PMID 34311721, 2021).